AGAP3 (ArfGAP with GTPase domain, ankyrin repeat and PH domain 3)
Description:
GTPase-activating protein for the ADP ribosylation factor family (Potential). GTPase which may be involved in the degradation of expanded polyglutamine proteins through the ubiquitin-proteasome pathway.
Synonyms: AGAP-3; CRAG; Cnt-g3; MRIP-1; CENTG3
Tractability: PROTAC: ubiquitination databases record sites on it; its protein half-life has been measured.
Gene: Protein-coding gene on chromosome 7 (151,085,831 to 151,144,436, forward strand). Ensembl gene ENSG00000133612.
Subcellular location: Cytoplasm
Gene Ontology:
Molecular function: GTPase activator activity; GTPase activity; polyubiquitin modification-dependent protein binding; GTP binding
Biological process: cellular response to reactive oxygen species; proteasome-mediated ubiquitin-dependent protein catabolic process; regulation of postsynaptic membrane neurotransmitter receptor levels
Cellular component: cell periphery; cytoplasm; nucleus; glutamatergic synapse; postsynaptic density
Genetic constraint (gnomAD): Loss-of-function variants: 24 observed, 93.92 expected, observed/expected ratio (o/e) 0.26, 90% interval 0.18 to 0.36. The upper end of that interval is the gene's LOEUF score, 0.36, which puts it in group 1 of 6, group 1 being the genes least tolerant of losing a copy. Missense variants: 858 observed, 1,245.8 expected, observed/expected ratio (o/e) 0.69, 90% interval 0.65 to 0.73. Synonymous variants: 552 observed, 531.37 expected, observed/expected ratio (o/e) 1.04, 90% interval 0.97 to 1.12.
Homologues: Orthologues: mouse Agap3 (96% identical), rat Agap3 (95% identical), chimpanzee AGAP3 (94% identical), pig AGAP3 (91% identical), rabbit AGAP3 (91% identical), dog AGAP3 (87% identical), guinea pig AGAP3 (83% identical), zebrafish agap3 (72% identical), tropical clawed frog agap3 (67% identical), macaque AGAP3 (25% identical). Paralogues in human: AGAP1 (64% identical), AGAP2 (47% identical), AGAP4 (36% identical), AGAP5 (36% identical), AGAP6 (36% identical), AGAP9 (33% identical), ACAP3 (18% identical), ACAP1 (17% identical), ACAP2 (16% identical), ASAP1 (16% identical), ASAP3 (16% identical), ASAP2 (15% identical), and 16 more.
Diseases named in the same sentence as AGAP3 in open-access papers:
AGAP3 is named in the same sentence as 38 diseases in open-access papers, as found by Europe PMC text mining. Sharing a sentence is not in itself a finding about the gene and the disease. The quoted sentences say what the papers report.
colon cancer (3 papers, 2009 to 2021). "Through lasso regression analysis, we selected seven optimal RNA construction models, namely, AGAP3, NHSL1, ENOPH1, NRG1, SNHG16, hsa-mir-1271-5p, and hsa-mir-26b-5p, to predict the prognosis of patients with colon cancer." (PMID 34692670, 2021).
acute leukemia (1 paper, 2023). A clonal (malignant) hematopoietic disorder with an acute onset, affecting the bone marrow and the peripheral blood. "AGAP3 was upregulated in acute leukemia samples compared to the blood control samples." (PMID 37113989, 2023). "We also obtained the interacting partners of AGAP3 from the STRING database, of which TTYH3, which has a significant effect on survival probabilities in AML samples (p-value = 0.03), was significantly upregulated in acute leukemia samples." (PMID 37113989, 2023).
Alzheimer disease (1 paper, 2023). A progressive, neurodegenerative disease characterized by loss of function and death of nerve cells in several areas of the brain leading to loss of cognitive function such as memory and language. "A recent study reported AGAP3 in Alzheimer’s disease correlates with resting and naive CD4 cells, NK cells, CD cells, etc.." (PMID 37113989, 2023).
chronic hepatitis B (1 paper, 2018). "What’s more, AGAP3 was reported having predictive power for inflammation grades of chronic hepatitis B." (PMID 30466390, 2018).
colorectal cancer (1 paper, 2022). A primary or metastatic malignant neoplasm that affects the colon or rectum. "Studies using patient-derived colorectal cancer organoids to compare BRAF fusions with various fusion partners (TRIM24, AGAP3, and DLG1) have shown that the 5′ partner plays a role in signaling and localization that affects signaling pathways and gene expression." (PMID 35326655, 2022).
glaucoma (1 paper, 2010). Increased pressure in the eyeball due to obstruction of the outflow of aqueous humor. "Although the association between AGAP3 and glaucoma is unclear, AGAP3 polymorphisms may act as risk factors in the development of NTG." (PMID 20309402, 2010).
systemic hypertension (1 paper, 2022). "While it is probable that this variant impairs NOS3 expression by interfering with NOS3 promotor activation, these data indicate that dysregulation of AGAP3 may also contribute to the increased risk for systemic hypertension." (PMID 35999210, 2022).
cancer (3 papers, 2021 to 2025). A tumor composed of atypical neoplastic, often pleomorphic cells that invade other tissues. "The DepMap analysis showed a significant correlation between AGAP3 expression and cancer cell line sensitivity to vandetanib, and that AGAP3 is overexpressed in more than 98% of the 1,376 cancer cell lines in the database merits further investigation." (PMID 34437536, 2021). "The eight cross-cancer CpGs were annotated to genes involved in transport (KCNA3, KCNAB3 and TRAPPC1), signal transduction (AGAP3 and LIME1), microtubule assembly (FES and SHROOM1), and metal binding (FURIN and AGAP3)." (PMID 35710732, 2022).
tumor (3 papers, 2009 to 2024). "We successfully validated the two BRAF fusion genes, detected by a single fusion-spanning read (such as in AGAP3-BRAF), by utilizing the exact breakpoint-locations provided by NanoFG and breakpoint-spanning PCR on the non-amplified tumor DNA." (PMID 32504042, 2020).
AGAP3 also shares sentences with these, for which no sentence is quoted: Cryptococcal meningitis (26 papers); cryptococcosis (21); meningitis (13); infection (5); AIDS (3); tuberculosis (2); adenoma (1); Ataxia (1); atherosclerosis (1); candidiasis (1); central nervous system infection (1); Hepatitis (1); herpes zoster (1); human immunodeficiency virus (HIV) disease (1); leukaemia (1); lung disease (1); lymphoma (1); mental illness (1); mycosis (1); neurodegenerative disease (1); Opportunistic infection (1); oral candidiasis (1); Pleural effusion (1); promyelocytic leukaemia (1); reproductive system disease (1); resistant hypertension (1); sarcoma (1); TB meningitis (1); thymic lymphoma (1).